EGFR (epidermal growth factor receptor)
Diseases named in the same sentence as EGFR in open-access papers (continued):
Sharing a sentence is not in itself a finding about the gene and the disease.
cancer (continued). "Recently, enhanced expression of proinflammatory chemokines by EGFR signaling has been suggested as a potential contributing factor to the inflammatory burden causing cancer progression and a higher mortality rate in patients with TNBC." (PMID 36358633, 2022). "It is recommended for advanced cancer patients and is used as a companion diagnostic test for lung cancer patients who have EGFR mutations." (PMID 36009594, 2022). "For example, IDH mutation 2-4, BRCA mutations 5,6, and EGFR amplification 7,8 have been widely reported for accurate diagnosis and precise treatment of cancers." (PMID 35637947, 2022). "Among them, EGFR was the first member to be identified, and also the first one linked to cancers, with the most intensive investigation." (PMID 35269825, 2022). "In the case of non-small-cell lung cancer, for example, the driver mutations in KRAS and EGFR seem to be mutually exclusive suggesting that, once a cancer population has one, the other is actively selected against." (PMID 35061724, 2022). "Dysregulation of EGFR signaling is associated with the development and progression of human cancers." (PMID 35309946, 2022). "While many of these trials are ongoing, some ITs are currently approved for CRC including mAbs that target cancer-associated antigens, namely panitumumab (anti-EGFR), cetuximab (anti-EGFR), and bevacizumab (anti-VEGF)." (PMID 35205776, 2022). "We selected the ERBB2 gene for further studies, which encodes the epidermal growth factor receptor that was previously found to be involved in the tumorigenesis of many different types of cancers." (PMID 35524932, 2022). "We assume that P6 and P9 are promising peptide carriers for drug delivery to EGFR overexpressed cancers and their EGFRvIII mutation." (PMID 35890400, 2022). "Overexpression of the EGFR protein and kinase-activating mutations are the two forms of pathogenic EGFR changes found in cancer." (PMID 35455247, 2022). "More importantly, overexpressed EGFR and gene mutation has been reported in several human tumors of epithelial origin and is the target of multiple cancer therapies currently adopted in clinical practice." (PMID 36568260, 2022). "Simultaneously, the mutation rate of EGFR in GBM is the highest among 33 cancer types documented in the TCGA dataset (up to 26.9%)." (PMID 35814475, 2022). "Epidermal growth factor receptor (EGFR) is a cell surface receptor essential for cell growth and differentiation, with its disregulation implicated in several carcinomas, hence a target for numerous cancer drugs." (PMID 35612280, 2022). "Epidermal growth factor receptor (EGFR) is a causal factor in carcinoma, yet many carcinoma patients are resistant to EGFR inhibitors." (PMID 35569509, 2022). "Activation of the EGFR downstream pathways leads to increased cell proliferation and migration, and its overexpression is associated with worse prognosis for various carcinomas." (PMID 35372019, 2022). "TRAF4 has long been found to be overexpressed in various carcinomas, whereas EGFR has been shown to be associated with NSCLC." (PMID 35748027, 2022). "Based on in-silico drug design, scientists are attempting to find more effective compounds against the EGFR protein with the goal of overcoming current mutations in the case of observed carcinoma treatment." (PMID 36457709, 2022). "It must be highlighted that the expression of EGF receptor (EGFR) is low in the healthy oral epithelium, it is augmented in high-risk OPMDs, and it is strongly upregulated in carcinoma cells." (PMID 35955471, 2022). "The trispecific antibody mediated an elevated antibody-dependent cellular cytotoxicity (ADCC) in comparison to the EGFR×CD16a bispecific variant by effectively bridging EGFR/PD-L1 double-positive cancer cells with CD16a-positive effector cells." (PMID 34040611, 2021).
cancer (continued). "Proliferative pathways that are frequently overactivated, or aberrantly activated, in cancer cells are associated with the tyrosine kinase activity of membrane receptors (such as EGFR, HER2) or of cytoplasmic proteins (such as the MEK/ERK family)." (PMID 33498502, 2021). "Activated EGFR mutations are often found in human cancers, especially NSCLC, and lead to the constitutive activation of downstream signals, including RAS." (PMID 34607583, 2021). "A clinical challenge for physicians treating patients with EGFR-mutant cancers is to appropriately identify and match patient mutations with the best EGFR TKI." (PMID 34526717, 2021). "Abnormally activated EGFR by receptor overexpression, mutation, and ligand-independent activation can result in the development of cancer." (PMID 34512175, 2021). "A number of EGFR inhibitors such as Lapatinib, Gefitinib, Afatinib and Erlotinib have been developed for use in cancer therapy as EGFR is overexpressed or constitutively active due to mutataions in various cancers." (PMID 34577570, 2021). "We were able to readily isolate ultralong CDR-H3 antibodies targeting cancer-associated receptor tyrosine kinase epidermal growth factor receptor (EGFR)." (PMID 34759924, 2021). "Cancer cells can escape the effects of chemotherapy through mutations and upregulation of a tyrosine kinase protein called the epidermal growth factor receptor (EGFR)." (PMID 34667537, 2021). "Both of these EGFR inhibitors restrain EGFR and its downstream activation in cancer cells, preventing cell proliferation and causing apoptosis." (PMID 33801379, 2021). "EGFR is expressed in healthy cells at a low level and plays an essential role in normal cell signaling; however, in cancer cells, mutations in EGFR lead to its overexpression." (PMID 34064412, 2021). "A negative correlation was observed between the expression levels of miR-449a and nicotinamide N-methyltransferase (NNMT), a metabolic enzyme linked to cancer, in EGFR-TKI-resistant NSCLC models." (PMID 34830377, 2021). "Recent studies have shown that microtubule inhibition causes EGFR inactivation or increases the sensitivity to EGFR targeting drugs in various cancers including OSCC." (PMID 33889303, 2021). "Materials and Methods: This was a retrospective cohort study enrolling non-small cell lung cancer (NSCLC) patients who harbored sensitizing EGFR mutation and had received EGFR-TKIs as first-line cancer therapy in the ICU with mechanical ventilator use." (PMID 34680533, 2021). "Misregulation and mutations of ErbB proteins were linked very early to cancer, and EGFR and ErbB2 in particular are now commonly targeted by tyrosine kinase inhibitors and/or antibodies." (PMID 34827688, 2021). "For example, patients with corneal abrasions and epithelial lesions saw marked healing with EGF treatment, as did corneal erosions associated with the use of cetuximab (an EGFR inhibitor) to treat cancer and traumatic corneal ulcers." (PMID 34572058, 2021). "This study showed that EGFR is possibly the core molecule that affects immune and cancer-related biological processes and it can eventually cause prognosis differences between HPV+ and HPV− cancers." (PMID 34646755, 2021). "An analysis of the COSMIC database displayed that the incidence of EGFR mutations significantly varies among the different types of cancers." (PMID 33572326, 2021). "Overexpression of EGFR is associated with resistance against chemotherapy and radiotherapy and is also associated with poor prognosis in many cancers." (PMID 33672373, 2021). "SPR was also utilized in other studies for the detection of exosomes based on other cancer-associated exosomal surface biomarkers such as epidermal growth factor receptor (EGFR) and programmed death-ligand 1 (PDL-1)." (PMID 33498573, 2021). "The human cancer cell line NCI-H1975 was used to validate the protocol of EGFR mutation detection in gDNA derived from CTC fractions." (PMID 34073111, 2021).
cancer (continued). "Using this “single-molecule diffusional mobility shift assay,” the researchers showed that a cancer-linked protein called EGFR tends to bind with a range of other proteins, depending on the type of cancer cell studied." (PMID 33603128, 2021). "The ErbB signaling pathway includes the tyrosine kinase family-like EGFR and is associated with drug, chemotherapy, and radiation resistance in cancer." (PMID 33763152, 2021). "Analysis of ctDNA identifies cancer-specific mutations, and is emerging as a promising tool for predicting relapse, monitoring response to treatment, and tracking resistance to anti-EGFR-based therapy in the metastatic setting." (PMID 34199435, 2021). "The identification of HER2 genomic amplification in cancers as a cause of EGFR-inhibitor resistance has become a promising therapeutic target, especially in HER2-amplified CRC." (PMID 33801379, 2021). "EGFR activation, through the interaction with natural ligands or by the existence of activating mutations, upregulates the expression of PD-L1 in cancer cells in vitro." (PMID 34211836, 2021). "Activated EGFR and its downstream signaling pathways were implicated in the proliferation, apoptosis suppression, invasion, and angiogenesis of cancer cells." (PMID 34885013, 2021). "Resistance of cancer cells towards chemotherapies and EGFR‐TKIs is the major cause that leads to recurrence and poor survival of NSCLC patients." (PMID 34076957, 2021). "While the use of liquid biopsies is already a reality for stage IV EGFR mutated cancer, there has been great development in cancer screening or in early disease, where the selection of patients undergoing heavy adjuvant treatments become crucial." (PMID 34735646, 2021). "Hyperactivation of the pathway accelerates intestinal tumourigenesis driven by Adenomatous polyposis coli loss (Apcmin/+ mice), while a genetic background of partial loss-of-function of EGFR or small-molecule inhibitor treatment reduces cancer incidence." (PMID 34096503, 2021). "OvoLs are also associated with human cancers, in particular those of epithelial origin that often display deregulated Wnt and EGFR signaling." (PMID 33372708, 2021). "It has been known for some time that the addition of epidermal growth factor (EGF) promotes the restoration of the corneal epithelium and patients using EGFR inhibitors as anti-cancer therapies are at increased risk of corneal erosions." (PMID 34572058, 2021). "Cell signaling pathways including transforming growth factor-β, epidermal growth factor receptor and Fas receptor, which promote proliferation and survival of cancer cells, have been linked to cell surface nucleolin." (PMID 34544457, 2021). "The abnormal activation of EGFR is significantly associated with cancer development and progression." (PMID 34830108, 2021). "Patients harbouring uncommon EGFR mutations were more likely to have a family history of cancer (p = 0.048)." (PMID 33889543, 2021). "Emergence of NGS-based approaches has boosted the potential use of liquid biopsies for mutation detection in several genes used as cancer biomarkers, such as EGFR and ALK, allowing the establishment of guidelines in targeted therapies using TKIs in NSCLC." (PMID 33916986, 2021). "This led to the discovery of second-generation EGFR inhibitors (afatinib, dacomitinib), which are irreversible and effective in cancer with T790M mutation; however, they are associated with side effects." (PMID 33803355, 2021). "Patients with uncommon EGFR mutations were more likely to have a family history of cancer than those with common EGFR mutations (p = 0.05)." (PMID 33889543, 2021). "EGFR gene-activating mutations have been detected in a variety of cancers, including lung, colorectal, head and neck, and pancreatic cancers." (PMID 33806040, 2021). "miRNA-7 expression leads to significant loss of ERBB2 in the cardiomyocytes instead of the EGFR that is observed in cancer cells." (PMID 34759299, 2021).
cancer (continued). "Cancer-associated gene binds to epidermal growth factor receptor (EGFR) and increases self-renewal, in addition to increasing autophagic flux." (PMID 34113619, 2021). "Epidermal growth factor (EGF) receptor (EGFR) is a transmembrane protein that belongs to the ErbB family of receptors and is well-studied for its association with a number of cancers." (PMID 34901094, 2021). "EGFR-activating mutations are involved in cancer development and resistance to cancer therapies, such as EGFR inhibitor treatment and chemotherapy." (PMID 34552618, 2021). "Although CRC and PAC rarely show EGFR mutations, both cancers overexpress this receptor and have been treated with cetuximab or panitumumab and erlotinib, respectively." (PMID 33923200, 2021). "Multiple compounds were associated with known human cancer signaling pathways, including EGFR (Icotinib and WZ4002), RAS (6H050), and MEK (PD0325901 and Refametinib, and U0126-EtOH)." (PMID 34211974, 2021). "Environmental air pollutants, which are associated with cancer and respiratory diseases, can also activate EGFR." (PMID 33705793, 2021). "Non-synonymous somatic mutations of EGFR observed in cancer patients have been reported to alter the normal EGFR function by increasing kinase activity." (PMID 33807850, 2021). "This is in accordance with previous work showing that when targeted therapy is effective in EGFR-mutated cancer cell lines, EGFR is downregulated, and further supports the effectiveness of the crizotinib and osimertinib combination in EGFR/MET-driven tumors." (PMID 34298655, 2021). "Tyrosine kinase inhibitors (TKIs) are well accepted as a molecular targeted therapies for patients with cancers harboring EGFR mutations." (PMID 34725466, 2021). "Because EGFR has a central role in the growth and survival of cancer cells, many materials have been developed to target EGFR directly." (PMID 34943012, 2021). "It has been widely recognized that not only genetic mutation but also aberrant functional modification of EGFR contributes to the pathogenesis of cancer." (PMID 33705793, 2021). "EGFR activation, resulting in either from mutation or ligand/receptor overexpression, is therefore associated with a variety of human cancers." (PMID 34295309, 2021). "EGFR is highly expressed and mutated in cancer cells, and this activates downstream signaling in many cancer cells." (PMID 33567635, 2021). "Another group demonstrated that aberrant phosphorylation of EGFR by its ligands, such as epithelial cell adhesion molecule, is associated with cancer progression." (PMID 33705793, 2021). "This comes about via the mutations in the tyrosine kinase domain of EGFR, or the activation of other signaling pathways in cancer cells which take on the role of the suppressed pathways." (PMID 34805097, 2021). "EGFR pathway signaling is implicated for cancer genesis such as proliferation, chemotactic migration, invasion, and evasion of apoptosis." (PMID 33639651, 2021). "It has been previously shown that the appearance of a weaker interaction is associated with the presence of dimerized EGFR on cancer cells’ surface." (PMID 33672373, 2021). "One way that this regulation is frequently circumvented in cancer is through gain-of-function mutations in three of the central players: RTKs (e.g., EGFR), Ras, and Raf." (PMID 34048471, 2021). "As well as many ESCC cell lines, over 70% of patient tissues exhibited the overexpression and amplification of EGFR, which is also strongly associated with aggressive cancer features and poor prognosis." (PMID 34722266, 2021). "EGFR mutations leading to EGFR overexpression result in cancer development, and EGFR mutations affect the poor prognosis of patients and mediate drug resistance of tumors." (PMID 34213719, 2021). "EGFR mutation and/or overexpression is observed in several human cancers and EGFR-targeted therapy has become a routine part of the treatment of several cancers." (PMID 34064074, 2021).
cancer (continued). "Similar to Ras, EGFR is also mutationally-activated and/or overexpressed in one-fifth of all human cancers." (PMID 34411095, 2021). "Although these drugs showed high efficacy in cancer therapy, EGFR mutations have emerged as a big challenge for these drugs." (PMID 34771085, 2021). "We analyzed through flow cytometry, western blotting and qPCR, the modulation of the most known cancer stem cells-associated genes and the EGFR while we observed the proliferation rate exploiting 2D and 3D cellular models." (PMID 34055629, 2021). "As EGFR is implicated in cancer progression and poor prognosis, several anti-EGFR treatment strategies have been clinically approved in recent years." (PMID 33808586, 2021). "Previous report found that 15% CCA have tyrosine kinase domain of EGFR gene mutations and activate EGFR downstream pathways when compared with EGFR wildtype cancer." (PMID 33639651, 2021). "Our study demonstrates that the malignant tumors with wild-type or mutated EGFR are sensitive to cinobufagin." (PMID 34925034, 2021). "In that case, ligand-independent, constitutively active forms of EGFR, which are linked to cancer, should be insensitive to RAL deficiency." (PMID 34096503, 2021). "The expression levels of EGFR are increased in various cancers and are associated with poor prognosis." (PMID 34830108, 2021). "Sustained proliferation signaling, which is identified as another hallmark of cancer, and EGFR inhibitors can be used to prevent this process." (PMID 33925065, 2021). "Currently, several fourth-generation EGFR-TKIs are being evaluated in regard to their efficacy against cancers carrying double or triple EGFR mutations." (PMID 34771085, 2021). "Other pathways commonly associated with cancer, such as EGFR, MAPK, mTOR, and PI3K-Akt, were also significantly enriched." (PMID 34104084, 2021). "Since the upregulation of EGFR is one of the most important biomarkers associated with cancer adverse prognosis, sensitive detection of EGFR-expressing exosomes plays a pivotal role in the early and non-invasive diagnosis of various cancers." (PMID 34769444, 2021). "In a patient treated for EGFR-mutated cancer, gefitinib concentration was 25.7 ng/mL in cord blood and 1.9 ng/mL in amniotic fluid, which is 20% of the maternal concentration after delivery." (PMID 33799824, 2021). "As a result, loss and mutations of E-cadherin promote cancer cell invasion due to uncontrolled activation of EGFR, which displays enhanced surface motility and changes in endocytosis." (PMID 35127732, 2021). "ADGRG6 can also form carcinogenic fusion variants with ROS1 to promote the development of EGFR-tyrosine kinase inhibitor resistance in cancer patients with EGFR mutation." (PMID 34809653, 2021). "It has been stated that the overexpression of EGFR is associated with resistance to chemotherapy, poor prognosis, and a more aggressive phenotype of cancers." (PMID 34715860, 2021). "Screening for the impact of other amplified cancer genes in HEK293 cells also demonstrated that EGFR, AKT2, CCND1, CCNE1, SKP2, and FGFR3 caused both increased abundance of phosphorylated ZFP36/TTP and ARE-post-transcriptional reporter activity." (PMID 34535639, 2021). "In contrast, numerous studies reported an association between EGFR-MEK pathway activity with an immune cold phenotype in multiple cancers, including HNSCC, and a lower benefit from ICI therapy in cancers with EGFR mutations." (PMID 34680330, 2021). "Only a small sub-population of cancer cells carry the heterozygous activating EGFR mutations whereas others harbor the wild type counterparts." (PMID 33461557, 2021). "Today, there are various approaches of actively targeting EGFR besides using the native ligand or mAbs to enhance the delivery of therapeutic and diagnostic agents to EGFR-overexpressing cancers." (PMID 33981532, 2021). "Gefitinib is an epidermal growth factor receptor (EGFR) inhibitor used in the treatment of cancers with overreactive or mutated EGFR." (PMID 34529084, 2021).